CDKL1 (cyclin dependent kinase like 1)
Synonyms: KKIALRE; P42
Tractability: Small molecule: a structure with a bound ligand is known; a high-quality ligand is known; it belongs to a druggable protein family. PROTAC: ubiquitination databases record sites on it; a small molecule that binds it is known.
Target class: Protein Kinase; CMGC protein kinase CDKL family; CMGC protein kinase group; Enzyme; Kinase
Gene: Protein-coding gene on chromosome 14 (50,326,265 to 50,416,461, reverse strand). Ensembl gene ENSG00000100490.
Subcellular location: Cytoplasm; Nucleus
Subcellular location (Human Protein Atlas): Nucleoplasm; Vesicles; Flagellar centriole; Mid piece
Gene Ontology:
Molecular function: cyclin-dependent protein serine/threonine kinase activity; ATP binding; protein kinase activity; protein serine kinase activity
Biological process: protein phosphorylation; regulation of cilium assembly; heart development; regulation of cell cycle
Cellular component: extracellular exosome; nucleoplasm; ciliary transition zone; cytoplasm; nucleus
Genetic constraint (gnomAD): Loss-of-function variants: 27 observed, 30.86 expected, observed/expected ratio (o/e) 0.87, 90% interval 0.64 to 1.21. The upper end of that interval is the gene's LOEUF score, 1.21, which puts it in group 5 of 6, group 1 being the genes least tolerant of losing a copy. Missense variants: 311 observed, 349.39 expected, observed/expected ratio (o/e) 0.89, 90% interval 0.81 to 0.98. Synonymous variants: 122 observed, 132.23 expected, observed/expected ratio (o/e) 0.92, 90% interval 0.8 to 1.07.
Homologues: Orthologues: chimpanzee CDKL1 (99% identical), macaque CDKL1 (98% identical), pig CDKL1 (93% identical), guinea pig CDKL1 (90% identical), dog CDKL1 (89% identical), mouse Cdkl1 (89% identical), rat Cdkl1 (88% identical), rabbit CDKL1 (86% identical), tropical clawed frog cdkl1 (79% identical), zebrafish cdkl1 (77% identical). Paralogues in human: CDKL4 (64% identical), CDKL2 (52% identical), CDKL3 (45% identical), CDKL5 (43% identical), CDK1 (36% identical), CDK3 (36% identical), CDK2 (35% identical), CDK5 (34% identical), CDK12 (34% identical), CDK13 (33% identical), CDK17 (33% identical), CDK18 (32% identical), and 14 more.
Diseases named in the same sentence as CDKL1 in open-access papers:
CDKL1 is named in the same sentence as 31 diseases in open-access papers, as found by Europe PMC text mining. Sharing a sentence is not in itself a finding about the gene and the disease. The quoted sentences say what the papers report.
lung cancer (5 papers, 2021 to 2025). A malignant neoplasm involving the lung. "CDKL1 is highly expressed in lung cancer and promotes the growth and proliferation of lung cancer cells, while also enhancing their radiosensitivity." (PMID 40370440, 2025). "Increased expression of CDKL1, combined with radiotherapy and anti-PD-L1 antibody therapy, can significantly improve the therapeutic outcomes for lung cancer." (PMID 40370440, 2025). "This study systematically evaluated the potential causal relationship between three key inflammatory factors (CDKL1, CXCL8 and TGFB1) and the risk of non‐small cell lung cancer (NSCLC) using Mendelian randomisation (MR) methodology." (PMID 40682474, 2025). "Cyclin-dependent kinase-like 1 (CDKL1) can suppress lung cancer cell growth and proliferation while enhancing radiosensitivity." (PMID 41346602, 2025). "Consistent with this idea, CDKL1 negatively regulated PD-L1 expression in two different human lung cancer cell lines (A549 and H1299) at both the mRNA and protein levels." (PMID 38520004, 2024). "As expected, the overexpression of CDKL1 significantly increased cellular sensitivity to irradiation, whereas the depletion of CDKL1 conferred radioresistance in lung cancer cells." (PMID 38520004, 2024). "In summary, our study provides a comprehensive understanding of the roles of CDKL1 in enhancing the radiosensitivity and inhibiting the immune evasion of lung cancer cells." (PMID 38520004, 2024). "This study provides evidence demonstrating that CDKL1 is expressed at low levels, inhibits tumorigenesis and enhances radiosensitivity in lung cancer." (PMID 38520004, 2024). "In this study, we provide evidence that the overexpression of CDKL1 suppresses tumorigenesis and enhances radiosensitivity in lung cancer." (PMID 38520004, 2024). "The expression of CDKL1 in all lung cancer cell lines was lower than that in human bronchial epithelioid cells (BEAS-2B)." (PMID 38520004, 2024). "More importantly, we confirmed that compared to monotherapy and dual therapy, triple therapy consisting of CDKL1 overexpression, RT, and anti-PD-L1 antibody treatment has the most potent synergistic antitumor effect on lung cancer." (PMID 38520004, 2024). "CDKL1 was downregulated and suppressed the growth and proliferation of lung cancer cells and increased radiosensitivity in vitro and in vivo." (PMID 38520004, 2024). "The observed overexpression of CDKL1 resulted in notable inhibition of lung cancer cell growth and a decrease in colony formation ability in vitro." (PMID 38520004, 2024). "This study shows for the first time that CDKL1 effectively inhibits the growth and proliferation of lung cancer cells both in vitro and in vivo." (PMID 38520004, 2024). "To further investigate the role of CDKL1 in the response to DNA damage in lung cancer, we initially conducted a neutral comet assay." (PMID 38520004, 2024). "Both CDKL1 overexpression and radiation treatment alone significantly impeded tumor growth and reduced the weight of the xenograft tumors, indicating that CDKL1 does indeed suppress tumorigenesis in lung cancer in vivo." (PMID 38520004, 2024). "Collectively, these findings suggest that the combined administration of CDKL1 overexpression, RT, and anti-PD-L1 antibody therapy has the strongest antitumor effect on lung cancer." (PMID 38520004, 2024). "An in vitro conditioned culture model and an in vivo C57BL/6J mouse xenograft model were developed to detect the activation markers of CD8+ T cells and evaluate the efficacy of CDKL1 overexpression combined with radiotherapy (RT) and an anti-PD-L1 antibody in treating lung cancer." (PMID 38520004, 2024). "However, the specific role of CDKL1 in regulating the response to RT and immunotherapy in lung cancer remains largely unexplored." (PMID 38520004, 2024). "Moreover, the combination of CDKL1 overexpression, RT, and anti-PD-L1 antibody therapy exhibited the most potent antitumor efficacy against lung cancer." (PMID 38520004, 2024).
lung cancer (continued). "Hence, these findings elucidate the role of CDKL1 as an upstream negative regulator of PD-L1, revealing a novel mechanism governing the expression of PD-L1 in lung cancer." (PMID 38520004, 2024). "Conversely, CDKL1 silencing accelerated the growth and proliferation of lung cancer cells." (PMID 38520004, 2024). "Collectively, these results suggest that CDKL1 may act as a tumor suppressor protein in lung cancer." (PMID 38520004, 2024). "Importantly, the combination of CDKL1 overexpression with RT and anti-PD-L1 antibody treatment elicits a potent immune response against tumor cells in lung cancer." (PMID 38520004, 2024). "Thus, our study revealed novel biological functions of CDKL1, suggesting that CDKL1 could serve as a promising target for the treatment of lung cancer." (PMID 38520004, 2024). "Notably, endogenous CDKL1 was observed to bind to endogenous YBX1 in lung cancer cells." (PMID 38520004, 2024). "This study aimed to investigate the role of cyclin-dependent kinase-like 1 (CDKL1) in the modulation of PD-L1 expression and the response to radioimmunotherapy in lung cancer." (PMID 38520004, 2024). "Mechanistically, CDKL1 interacted with the transcription factor YBX1 and decreased the binding affinity of YBX1 for the PD-L1 gene promoter, which consequently inhibits the expression of PD-L1, ultimately leading to the activation of CD8+ T cells and the inhibition of immune evasion in lung cancer." (PMID 38520004, 2024).
colorectal cancer (3 papers, 2018 to 2022). A primary or metastatic malignant neoplasm that affects the colon or rectum. "As reported, CDKL1 overexpression could decrease the chemosensitivity of oral squamous cell carcinoma cells to hydroxycamptothecin, the reduction of CDKL1 attenuated tumor proliferation and invasion in colorectal cancer, inhibited proliferation, and improved apoptosis of GC." (PMID 33178818, 2020).
neuroblastoma (2 papers, 2024 to 2025). Neuroblastoma (NB) is the most common solid, extracranial childhood tumor. "CDKL1, which was initially discovered in the astrocytes of neuroblastoma patients, has functions comparable to those of other CDK proteins." (PMID 38520004, 2024).
periodontitis (2 papers, 2025 to 2026). An acute or chronic inflammatory process that affects the tissues that surround and support the teeth. "Other significant genes included DNASE1L3, CDKL1, and DPEP2, highlighting the compounding effects of poor glycemic control, dyslipidemia, and periodontitis on molecular dysregulation." (PMID 40458179, 2025).
adenoma (1 paper, 2024). A neoplasm arising from the epithelium. "Noteworthy, the numbers of RNA interactors of some MP-RNAs (WDR62, TGFBR3, RN7SL5P, RMRP, MIR663AHG, AJ009632.2, CDKL1, OPRD1, PLOD1, AL117692.1, ATP13A2, EPB41) in cancer tissue were significantly increased compared with that in paracancer and adenoma." (PMID 38773399, 2024).
aneurysm (1 paper, 2025). Bulging or ballooning in an area of an artery secondary to arterial wall weakening. "Recurrent vascular manifestations in our series of individuals with heterozygous CDKL1 include aneurysms and dissections of the thoracic/abdominal aorta and of the carotid arteries." (PMID 41056017, 2025).
ascending aortic aneurysms (1 paper, 2025). "We visualized CDKL1 in aortic tissue from 3 individuals with ascending aortic aneurysms and 2 control individuals." (PMID 41056017, 2025).
breast carcinoma (1 paper, 2018). "CDKL1 overexpressed is greater in breast cancer tissues than in benign tissues." (PMID 29790675, 2018).
ciliopathies (1 paper, 2025). "However, patients with CDKL1 and CDKL2 variants have been reported that present with global developmental delay, intellectual disability, childhood-onset epilepsy, and dyspraxia—symptoms similar to those associated with CDD and other ciliopathies." (PMID 41385589, 2025).
tumor (6 papers, 2015 to 2024). "To investigate the potential role of CDKL1 in facilitating radiosensitization in vivo, we generated A549 cells that overexpress CDKL1 and subsequently established a subcutaneous transplanted tumor model in nude mice." (PMID 38520004, 2024). "Subsequently, we inoculated a stable Lewis cell line overexpressing CDKL1 into C57BL/6J mice to establish a subcutaneous tumor model." (PMID 38520004, 2024). "We also identified two other genes (TP53I11 and CDKL1) that contain tumor-specific repeat instabilities in their exons, and where repeat instability had not been documented so far." (PMID 26376692, 2015). "Furthermore, we identified YBX1 as a novel CDKL1-interacting protein and elucidated a new mechanism by which CDKL1 affects tumor immune evasion through the YBX1/PD-L1 axis." (PMID 38520004, 2024). "To elucidate the role of CDKL1 in immune evasion, we ground transplanted tumors into single-cell suspensions and subsequently conducted flow cytometry staining to assess the proportion of CD8+ T cells and the levels of their secreted factors within the tumor." (PMID 38520004, 2024). "Cluster 1 was characterized by upregulation of tumor-suppressing genes: HNF1B, CCNDBP1, PATJ, EPB41L3, MARVELD2, PTEN in conjunction with cell-cycle genes – GSPT1, GPR19, EAPP, KIT, CDKL1, and stem cell markers – RBBP5, NANOG, NCSTN, ERG, including quiescent stem cell markers—FOXP1, SMARCA2." (PMID 36348001, 2022).
cancer (5 papers, 2018 to 2024). A tumor composed of atypical neoplastic, often pleomorphic cells that invade other tissues. "CDKL1 is closely associated with the growth and proliferation of malignant tumors." (PMID 38520004, 2024). "CDKL1 is expressed in the lungs, brain and ovaries and is implicated in processes such as cilia formation, cilium length regulation, brain development, and cancer progression." (PMID 38520004, 2024). "The previously unknown risk loci are implicated in cancer development and progression (e.g. CDKL1), pigmentation (e.g. TPCN2), cardiometabolic (e.g. FADS2), and immune-regulatory pathways for innate immunity (e.g. IFIH1), and HIV-1 viral load modulation (e.g. CCR5)." (PMID 36496446, 2022).
vasculopathy (1 paper, 2025). "Taken together, the collected clinical data may suggest that CDKL1-associated vasculopathy might be characterized by an involvement of large to medium-sized arteries in addition to the clinical manifestations known for hereditary aortopathies." (PMID 41056017, 2025).
CDKL1 also shares sentences with these, for which no sentence is quoted: melanoma (2 papers); clear cell renal carcinoma (1); connective tissue disorder (1); developmental delay (1); dolichostenomelia (1); Dural ectasia (1); dyslipidemia (1); dyspraxia (1); HCMV infection (1); Intellectual disability (1); leukemia (1); lung adenocarcinoma (1); lung squamous cell carcinoma (1); Marfan syndrome (1); oral squamous cell carcinoma (1); Pectus excavatum (1); renal cell cancer (1); scoliosis (1); thoracic aortic aneurysm (1).